B4GALT4 (beta-1,4-galactosyltransferase 4)
Description:
Galactose (Gal) transferase involved in the synthesis of terminal N-acetyllactosamine (LacNac) unit present on glycan chains of glycoproteins and glycosphingolipids. Catalyzes the transfer of Gal residue via a beta1->4 linkage from UDP-Gal to the non-reducing terminal N-acetyl glucosamine 6-O-sulfate (6-O-sulfoGlcNAc) in the linearly growing chain of both N- and O-linked keratan sulfate proteoglycans. Cooperates with B3GNT7 N-acetyl glucosamine transferase and CHST6 and CHST1 sulfotransferases to construct and elongate mono- and disulfated disaccharide units [->3Galbeta1->4(6-sulfoGlcNAcbeta)1->] and [->3(6-sulfoGalbeta)1->4(6-sulfoGlcNAcbeta)1->] within keratan sulfate polymer. Transfers Gal residue via a beta1->4 linkage to terminal 6-O-sulfoGlcNAc within the LacNac unit of core 2 O-glycans forming 6-sulfo-sialyl-Lewis X (sLex). May contribute to the generation of sLex epitope on mucin-type glycoproteins that serve as ligands for SELL/L-selectin, a major regulator of leukocyte migration. In the biosynthesis pathway of neolacto-series glycosphingolipids, transfers Gal residue via a beta1->4 linkage to terminal GlcNAc of a lactotriaosylceramide (Lc3Cer) acceptor to form a neolactotetraosylceramide. Efficiently galactosylates both non-sulfated and 6-O-sulfated terminal GlcNAc moities on G0 complex-type N-glycans.
Synonyms: Beta4Gal-T4; b4Gal-T4
Tractability: Antibody: UniProt places it where antibodies can reach, with high confidence; UniProt predicts a signal peptide or a membrane-spanning region; its Gene Ontology location is reachable by antibodies, with medium confidence. PROTAC: its protein half-life has been measured.
Gene: Protein-coding gene on chromosome 3 (119,211,628 to 119,240,952, reverse strand). Ensembl gene ENSG00000121578.
Subcellular location: Golgi apparatus membrane; Secreted
Subcellular location (Human Protein Atlas): Golgi apparatus
Pathways (Reactome):
Metabolism: Keratan sulfate biosynthesis
Metabolism of proteins: N-Glycan antennae elongation
Gene Ontology:
Molecular function: beta-N-acetylglucosaminylglycopeptide beta-1,4-galactosyltransferase activity; N-acetyllactosamine synthase activity; protein binding; UDP-galactosyltransferase activity; galactosyltransferase activity; glycosyltransferase activity
Biological process: keratan sulfate proteoglycan biosynthetic process; lactosylceramide biosynthetic process; lipid metabolic process; carbohydrate metabolic process
Cellular component: extracellular region; Golgi apparatus; Golgi membrane; membrane
Genetic constraint (gnomAD): Loss-of-function variants: 26 observed, 38.99 expected, observed/expected ratio (o/e) 0.67, 90% interval 0.49 to 0.93. The upper end of that interval is the gene's LOEUF score, 0.93, which puts it in group 3 of 6, group 1 being the genes least tolerant of losing a copy. Missense variants: 367 observed, 429.33 expected, observed/expected ratio (o/e) 0.85, 90% interval 0.78 to 0.93. Synonymous variants: 148 observed, 162.34 expected, observed/expected ratio (o/e) 0.91, 90% interval 0.8 to 1.04.
Homologues: Orthologues: chimpanzee B4GALT4 (98% identical), macaque B4GALT4 (89% identical), dog B4GALT4 (86% identical), guinea pig B4GALT4 (85% identical), pig B4GALT4 (84% identical), mouse B4galt4 (83% identical), rat B4galt4 (83% identical), rabbit B4GALT4 (72% identical), tropical clawed frog b4galt4 (60% identical), zebrafish b4galt4 (58% identical), Caenorhabditis elegans bre-4 (35% identical), Drosophila melanogaster beta4GalNAcTA (32% identical). Paralogues in human: B4GALT3 (47% identical), B4GALT1 (42% identical), B4GALT2 (42% identical), B4GALT6 (35% identical), B4GALT5 (34% identical), B4GALT7 (26% identical).
Diseases named in the same sentence as B4GALT4 in open-access papers:
B4GALT4 is named in the same sentence as 15 diseases in open-access papers, as found by Europe PMC text mining. Sharing a sentence is not in itself a finding about the gene and the disease. The quoted sentences say what the papers report.
colorectal cancer (2 papers, 2016 to 2020). A primary or metastatic malignant neoplasm that affects the colon or rectum. "The expression of B4GALT3 enhanced migration and invasion of human neuroblastoma cells, and highly expression of B4GALT4 was associated with colorectal cancer metastasis and poor prognosis." (PMID 27092876, 2016). "A recent study suggested a genomic explanation for such up-regulation of B4GalT4 in colorectal cancer cells." (PMID 32827291, 2020).
bladder cancer (1 paper, 2025). "This tumor-restricted expression pattern may be explained by the upregulation of B4GALT3 and B4GALT4, as shown in the TCGA bladder cancer dataset." (PMID 40706589, 2025).
breast carcinoma (1 paper, 2023). "B4galt4 is most homologous to the B4galt3 gene, and the growth of the strongly immunogenic E0771 breast cancer cell line in B4galt4 KO mice was unaffected." (PMID 37901252, 2023).
colon cancer (1 paper, 2018). "Among the β4GalT family members, the clinical relevance of β4GalT4 was reported that the expression of β4GalT4 increases in colon cancer, and enhanced expression of β4GalT4 is associated with metastasis and poor prognosis of colon cancer." (PMID 30082623, 2018). "Thus, by focusing on the transcriptional mechanism of the β4GalT4 gene, a screening method for anti-colon cancer drugs that inhibits the expression of the β4GalT4 gene can be developed." (PMID 30082623, 2018). "Therefore, β4GalT4 is considered to be a potential target molecule for anti-colon cancer drugs." (PMID 30082623, 2018). "Recently, we identified the core promoter region of the β4GalT4 gene and showed that the Specificity protein 1 (Sp1)-binding site (−88/−76) in the 0.17 kb core promoter region is critical for the promoter activity in SW480 human colon cancer cells." (PMID 30082623, 2018).
hepatocellular carcinoma (1 paper, 2023). A malignant tumor that arises from hepatocytes. "High expression of B4GALT4 is associated with poor prognosis in hepatocellular carcinoma (HCC)." (PMID 37901252, 2023).
meningioma (1 paper, 2023). A generally slow growing tumor attached to the dura mater. "WHO grade I and II meningiomas had 16 antigens in common with three antigens exclusively presented by WHO grade I meningiomas (TC1D2, B4GALT4, and MTU1) (online resource 1)." (PMID 37368072, 2023).
osteoporosis (1 paper, 2024). A condition of reduced bone mass, with decreased cortical thickness and a decrease in the number and size of the trabeculae of cancellous bone (but normal chemical composition), resulting in increased fracture incidence. "Our study performed a comprehensive analysis of important EMGs in osteoporosis and developed a diagnosis signature consisting 5 EMGs, including B4GALT4, ADH4, ACAD11, B4GALT2, and PPP1R3C with a relative higher AUC." (PMID 38589566, 2024). "Furthermore, the DANCR/hsa-miR-23b-3p/B4GALT4 axis may provide novel molecular insights into osteoporosis development." (PMID 38589566, 2024). "Furthermore, the DANCR/hsa-miR-23b-3p/B4GALT4 axis might provide novel molecular insights into the process of osteoporosis development." (PMID 38589566, 2024). "Therefore, we hypothesized that the DANCR/hsa-miR-23b-3p/B4GALT4 axis may provide novel molecular insights into the development of osteoporosis." (PMID 38589566, 2024). "Overall, this study constructed a model that can predict the incidence of osteoporosis and identified B4GALT4, ADH4, ACAD11, B4GALT2, and PPP1R3C as potential biomarkers for osteoporosis development." (PMID 38589566, 2024). "Thus, we propose that B4GALT4, ADH4, ACAD11, B4GALT2, and PPP1R3C are involved in the development of osteoporosis, potentially by modulating metabolic pathways." (PMID 38589566, 2024). "B4GALT4, ADH4, ACAD11, B4GALT2, and PPP1R3C may be valuable biomarkers for the development of osteoporosis." (PMID 38589566, 2024).
prostate carcinoma (1 paper, 2022). A carcinoma that arises from epithelial cells of the prostate gland. "Notably, the CERES scores of B4GALT4 and SULT1E1 were not less than zero in some prostate cancer cell lines, indicating that B4GALT4 and SULT1E1 might not play an inhibitory role in PRAD." (PMID 36439479, 2022).
tumor (8 papers, 2018 to 2025). "The expression of B4GALT1 and B4GALT4 in paired normal and tumor colon tissues was further examined by IHC." (PMID 39231945, 2024). "We examined the growth of various strongly or weakly immunogenic tumor cell lines transplanted into B4galt1, B4galt3, and B4galt4 knockout (KO) mice." (PMID 37901252, 2023). "In our study, we confirmed that silencing of B4GALT3 significantly enhanced cell viability and invasive capacity, indicating that B4GALT4 exerted a tumor suppressive role in BC." (PMID 30312173, 2018). "We also examined tumor growth in B4galt1 or B4galt4 KO mice." (PMID 37901252, 2023). "B4GALT4, BCL2L1, COPG1, CRB3, GET4, and TFRC showed almost the same expression levels between tumor and normal tissues." (PMID 33850477, 2021). "The results showed that CLDN9, AK4, PC, GPC1, and SRD5A3 were upregulated in EC tissues compared to in normal endometrium tissues, whereas B4GALT1, GMPPB, B4GALT4, and CHST6 were downregulated in tumor tissues." (PMID 31807118, 2019).
cancer (1 paper, 2024). A tumor composed of atypical neoplastic, often pleomorphic cells that invade other tissues. "We evaluated the expression of genes that are most frequently altered in malignant cancers and found that the mRNA and protein levels of B4GALT1 and B4GALT4 were increased in CRC cells." (PMID 39231945, 2024).
B4GALT4 also shares sentences with these, for which no sentence is quoted: demyelinating disorders (1 paper); endometrial cancer (1); glioma (1); melanoma (1); neuroblastoma (1).